TRPM6 (transient receptor potential cation channel subfamily M member 6)
Diseases named in the same sentence as TRPM6 in open-access papers (continued):
Sharing a sentence is not in itself a finding about the gene and the disease.
neuroblastoma (4 papers, 2014 to 2025). Neuroblastoma (NB) is the most common solid, extracranial childhood tumor. "Although direct evidence in glioma is limited, studies in other cancers (e.g., neuroblastoma) suggest that TRPM6 expression can be upregulated by oncogenes such as N-Myc, thereby influencing ionic balance and cell proliferation." (PMID 41331166, 2025). "Given the role of Mg2+ in cell proliferation, the present study carefully examined two Mg2+-transporting channel kinases, TRPM7 and TRPM6, in neuroblastoma cells." (PMID 25277194, 2014). "The presence and regulation of TRPM6 in SHEP-21N cells thus would suggest that this channel may also serve a role in the pathological context of neuroblastoma by regulating cellular Mg2+ levels in conjunction with TRPM7." (PMID 25277194, 2014). "Collectively, genetic or pharmacological suppression of TRPM7/TRPM6 channels inhibits cell proliferation, underscoring the importance of these channels in promoting proliferation and pointing towards a potential therapeutic avenue for the treatment of neuroblastoma." (PMID 25277194, 2014). "In order to investigate the role of N-Myc in TRPM7/TRPM6 regulation, we chose the SHEP-21N cell line, a clone derived from the SHEP-2 neuroblastoma, in which N-Myc is constitutively expressed but can be experimentally repressed." (PMID 25277194, 2014). "Genetic suppression of TRPM6/TRPM7 through siRNA inhibits cell proliferation, suggesting that N-Myc can promote neuroblastoma cell proliferation through up-regulation of divalent cation-transporting channels." (PMID 25277194, 2014). "We set out to examine the expression level of the Mg2+-influx channels TRPM6 and TRPM7 in the largest publicly available neuroblastoma expression profiling dataset, the Kocak-649 cohort." (PMID 25277194, 2014). "Our results reveal that TRPM7 is essential for neuroblastoma proliferation and the additional expression of TRPM6 modulates the phenotype of native MagNuM currents, favoring divalent cation transport mediated by TRPM6 and TRPM7 and promoting neuroblastoma cell proliferation." (PMID 25277194, 2014). "While TRPM6 was initially discovered in the absorptive epithelia in the kidney and intestine, the present study now demonstrates that the protein is also expressed in SHEP-21N neuroblastoma." (PMID 25277194, 2014). "The expression patterns of TRPM6 and TRPM7 in MYCN-amplified neuroblastoma cell lines and SHEP-21N cells suggests that their expression might not necessarily relate to N-Myc expression, as some MYCN-amplified cell lines had low TRPM6 expression levels (data not shown)." (PMID 25277194, 2014). "The data presented in this study suggest that TRPM7 channels have a significant impact on cell proliferation of neuroblastoma, regardless of whether or not they express N-Myc, whereas additional TRPM6 expression further synergizes with TRPM7 in augmenting the proliferative activity." (PMID 25277194, 2014). "In the human neuroblastoma cell line SHEP-21N, the expression of N-myc oncogene correlated with TRPM7 but not with TRPM6 mRNA expression, probably due to the few numbers of malignant tumors with significant TRPM6 expression." (PMID 36844925, 2022).
colitis (3 papers, 2023 to 2025). Inflammation of the colon. "Impact of HFD on DSS‐induced colitis may be linked to intestinal dysbiosis and specific genes such as Abca8b, Ace2, Apoa1, Apoa4, Apoc3, Aspa, Dpp4, Maob, Slc34a2, Slc7a9, and Trpm6." (PMID 39479684, 2024). "Overall, the findings indicate that the impact of HFD on DSS‐induced colitis may be linked to intestinal dysbiosis and specific genes such as Abca8b, Ace2, Apoa1, Apoa4, Apoc3, Aspa, Dpp4, Maob, Slc34a2, Slc7a9, and Trpm6." (PMID 39479684, 2024). "Magnesium plays a role in inflammatory responses, and alterations in TRPM6 may affect magnesium levels in the gut, influencing inflammatory processes in colitis." (PMID 39479684, 2024).
gestational diabetes (3 papers, 2013 to 2024). Carbohydrate intolerance first diagnosed during pregnancy. "They observed a significant association between carriers of the TRPM6 rs2274924 variant and elevated total glycosylated hemoglobin and greater prevalence of gestational diabetes in 997 women following delivery." (PMID 24322525, 2013).
Gitelman syndrome (3 papers, 2022 to 2025). Gitelman syndrome (GS), also referred to as familial hypokalemia-hypomagnesemia, is characterized by hypokalemic metabolic alkalosis in combination with significant hypomagnesemia and low urinary calcium excretion. "In this context, Gitelman syndrome kidney sections and control sections of hematuria-patient kidneys with minor glomerular lesions were allocated to TRPM6 staining." (PMID 40025338, 2025).
Hypertension (3 papers, 2017 to 2020). The presence of chronic increased pressure in the systemic arterial system. "In a hypertension murine model, aldosterone infusion affected TRPM6 expression in the plasmatic membrane, triggering hypomagnesemia and worsening hypertension-induced renal injury." (PMID 33291725, 2020). "TRPM6 and TRPM7 were both found in the vascular smooth muscle cells and were shown to regulate hypertension via Mg2+ homeostasis." (PMID 29206233, 2017).
atherosclerosis (2 papers, 2016 to 2017). A disease characterized by the build-up of fatty material and calcium deposition in the arterial wall resulting in partial or complete occlusion of the arterial lumen. "It has been suggested that low serum Mg2+ and TRPM6 function are associated with atherosclerosis in humans." (PMID 27991852, 2016).
atrial fibrillation (2 papers, 2019 to 2021). A disorder characterized by an electrocardiographic finding of a supraventricular arrhythmia characterized by the replacement of consistent P waves by rapid oscillations or fibrillatory waves that vary in size, shape and timing and are accompanied by an irregular ventricular response. "Recently, higher amount of mRNA and protein levels of TRPM6 in addition to significant increase in markers of myocardial fibrosis as TGF-β1, collagen I and III, were detected in atrial fibrillation patients, suggesting possible contribution of TRPM6 to atrial fibrosis." (PMID 30881310, 2019).
breast carcinoma (2 papers, 2015 to 2020). "The members of TRPM ion channel family such as TRPM2, TRPM7 and TRPM8 play vital roles in the growth, survival and metastasis of breast cancer cells, while somatic mutations affecting TRPM6 occur in breast cancer patients." (PMID 32484822, 2020). "In summary, we discovered novel somatic mutations in the TRPM6, HYDIN, ENTHD1 and NDUFB10 genes in early onset Chinese breast cancer patients through whole exome sequencing." (PMID 26870154, 2015). "Meanwhile, another study, which included 108 breast cancer patients from Mexico and Vietnam using whole-genome and whole-exome sequencing, did not discover any mutations in the TRPM6 gene." (PMID 26870154, 2015).
emphysema (2 papers, 2022). "Mg2+ deficiency can lead to emphysema as recently reported for TRPM6 knockout mice." (PMID 35031603, 2022). "Thus, e.g., TRPV4 channels are essential for alveolar epithelial barrier function as protection from lung edema and lungs from mice lacking TRPC6 are protected from lung ischaemia-reperfusion-induced oedema (LIRE), while magnesium deficiency in TRPM6 results in severe emphysema." (PMID 35053420, 2022).
endometriosis (2 papers, 2018 to 2020). The growth of functional endometrial tissue in anatomic sites outside the uterine body. "Repeated genes from the MS-phase (CCN1, CRISP3, EGR1, FOS, FOSB, and TRPM6) could be associated with affected receptivity in endometriosis." (PMID 32474803, 2020).
ischemia (2 papers, 2012 to 2024). A hypoperfusion of the BLOOD through an organ or tissue caused by a PATHOLOGIC CONSTRICTION or obstruction of its BLOOD VESSELS, or an absence of BLOOD CIRCULATION. "Extracellular Ca2+ and Mg2+ concentrations are not fixed in vivo (especially at mucosal-air interfaces) and can be substantially decreased in ischemia and genetic disorders of the TRPM6 gene." (PMID 22328938, 2012). "Additional research has demonstrated that TRPM2, TRPM6, TRPM7, and TRPM8 may impact hepatic ischemia-reperfusion injury, with TRPM2 knockout exhibiting a reduction in such injury through the activation of autophagy and inhibition of autophagy-negative regulation of the NLRP3 inflammasome pathway." (PMID 38255767, 2024).
pancreatic cancer (2 papers, 2014 to 2022). "We investigated the expression of TRPM7, TRPM6 and POSTN in pancreatic cancer samples (PAAD-TCGA) and normal pancreas samples from GTEX using GEPIA2021, which enables to filter the cell types of interest in normal tissue from GTEX or cancer types from TCGA." (PMID 35883700, 2022). "We investigated the expression of TRPM7, TRPM6 and periostin (POSTN), a marker of activated CSPs, in pancreatic cancer samples using GEPIA tool." (PMID 35883700, 2022). "Our finding predicts that, the TRP (Ca2+) channel-related genes (TRPV5 and TRPM6) and KCNK (K+) channel-related genes in the ion transport pathway are possible biomarkers of pancreatic cancer survival." (PMID 24565114, 2014).
Spina bifida occulta (2 papers, 2020 to 2023). The closed form of spina bifida with incomplete closure of a vertebral body with intact overlying skin. "TRPM6, encodes a channel protein crucial for magnesium homeostasis and mutations in Trpm6 in mice result in exencephaly and spina bifida occulta." (PMID 32650820, 2020). "In mice, homozygous deletion of Trpm7 is embryonic lethal, and Trpm6 knockout mutants exhibit exencephaly and/or spina bifida occulta." (PMID 37377737, 2023).
Stroke (2 papers, 2022 to 2025). Sudden impairment of blood flow to a part of the brain due to occlusion or rupture of an artery to the brain. "Significant risk factors for PSE include age < 65age less than 65 years, stroke severity measured by the National Institutes of Health Stroke Scale (NIHSS), cortical involvement, and genetic factors such as TRPM6 polymorphism." (PMID 36338344, 2022). "The significant risk factors for PSE include age less than 65 years, stroke severity measured by the National Institutes of Health Stroke Scale (NIHSS), cortical involvement, and genetic factors such as TRPM6 polymorphism." (PMID 36338344, 2022).
Acidosis (1 paper, 2018). Abnormal acid accumulation or depletion of base. "In animal models, metabolic acidosis, which is induced by oral NH4Cl loading, induces reduction of TRPM6 mRNA levels and enhances urinary Mg2+ excretion." (PMID 30241394, 2018).
adenoma (1 paper, 2016). A neoplasm arising from the epithelium. "The commonly repressed genes in these two adenoma samples include BCL2L11, TP53INP2, HIST1H1C, TRPM6, MIR22HG, and MIR5047." (PMID 27100181, 2016).
calpainopathy (1 paper, 2025). "In calpainopathy, there is a defective function of PI3K, which may result in decreased expression of TRPM6, leading to hypomagnesemia." (PMID 40520344, 2025).
cardioembolic stroke (1 paper, 2019). "The association of genetically predicted serum magnesium concentration with cardioembolic stroke persisted after exclusion of the outlier in TRPM6 (OR 0.56, 95% CI 0.43–0.73)." (PMID 30804065, 2019).
cholangiocarcinoma (1 paper, 2025). A carcinoma that arises from the intrahepatic biliary tree (intrahepatic cholangiocarcinoma) or from the junction, or adjacent to the junction, of the right and left hepatic ducts (hilar cholangiocarcinoma). "Notably, TRPM6 was strongly and positively correlated with the StromalScore, ImmuneScore, and ESTIMATEScore in cholangiocarcinoma (CHOL)." (PMID 41562086, 2025).
colorectal adenocarcinoma (1 paper, 2017). The most common type of colorectal carcinoma. "To establish a possible link between TRPM6, TRPM7, magnesium (Mg2+) and colon carcinogenesis, we first set out to characterize channel kinases in vitro using the human colorectal adenocarcinoma cell line HT-29." (PMID 28810912, 2017).
diabetic nephropathy (1 paper, 2022). "This is supported by the co-expression of Klotho and TRPM6 in distal tubular cells, and by the fact that the renal expression of Klotho and TRPM6 are strongly correlated in healthy individuals as well as in patients with diabetic nephropathy." (PMID 36699036, 2022).
Failure to thrive (1 paper, 2016). Failure to thrive (FTT) refers to a child whose physical growth is substantially below the norm. "Trpm6-deficient mice displayed shorter lifespans, failure to thrive, low physical activity, kyphosis, lung emphysema, sarcopenia and degeneration of lymphoid organs." (PMID 27991852, 2016).
hyperaldosteronism (1 paper, 2018). Overproduction of aldosterone by the adrenal glands, which may lead to hypokalemia and/or hypernatremia. "Nijenhuis also hypothesized that hyperaldosteronism might contribute to the downregulation of TRPM6." (PMID 29378538, 2018).
Hypermagnesemia (1 paper, 2019). An abnormally increased magnesium concentration in the blood. "Therefore, the use of PPIs should be avoided in the treatment of patients with TRPM6/TRPM7 mutation to reduce the incidence of hypermagnesemia." (PMID 30921222, 2019).
Infertility (1 paper, 2016). "Hence, additional TRPM6 phenotypes, such as infertility or embryonic death, might have been overlooked." (PMID 27991852, 2016).
Intellectual disability (1 paper, 2023). "Observing the frequencies of the characteristics in Group 2A and in Group 3, intellectual disability, autistic behaviour, and seizure are the most specific findings of the involvement of RORB and TRPM6 in 9q21.13 microdeletion syndrome." (PMID 37239476, 2023).
ischemic cardiomyopathy (1 paper, 2017). Ischemic cardiomyopathy is a cardiomyopathy in which a weakness in the muscle of the heart due to inadequate oxygen delivery to the myocardium with coronary artery disease being the most common cause. "It would be interesting to test whether TRPM6 expression is upregulated in ischemic cardiomyopathy, since by contaminating TRPM7 measurements or by forming heteromeres with TRPM7 it could confer changes in sensitivity to modulators such as divalent cations and protons." (PMID 28129376, 2017).
lipodystrophy (1 paper, 2016). A congenital or acquired disorder characterized by abnormal loss or redistribution of the adipose tissue in the body. "In addition, Trpm6-deficient animals developed signs of catabolic metabolism such as lipodystrophy, increased insulin sensitivity and hypothermia, and showed suppression of the somatotropic axis accompanied by induction of xenobiotic detoxification gene networks in the liver." (PMID 27991852, 2016).
myocardial infarction (1 paper, 2021). Gross necrosis of the myocardium, as a result of interruption of the blood supply to the area, as in coronary thrombosis. "Studies have shown that up-regulation of miR-202-3p or knockdown of transient receptor potential melastatin 6 (TRPM-6) could reduce oxidative stress and inflammation, change cardiac hemodynamics, suppress myocardial infarction, and decrease apoptosis and myocardial fiber inhibition." (PMID 33893248, 2021).
Nephropathy (1 paper, 2013). A nonspecific term referring to disease or damage of the kidneys. "Our results are in line with the hypothesis that EGF influences the renal expression or activation of TRPM6 and plays a significant role in Mg2+ loss in medication-induced nephropathy." (PMID 23457647, 2013). "Our research group and others reported that hypomagnesemia in calcineurin inhibitor (CNI)-induced nephropathy is related to the downregulation of epidermal growth factor (EGF) and TRPM6." (PMID 23457647, 2013).
occipital encephalocele (1 paper, 2020). "We found 2 PDRVs in TRPM6 in two cases of occipital encephalocele and occipital, cervical and thoracic spina bifida aperta and 1 PDRV in one case of occipital encephalocele and holorachischisis (P = 0.0004 and P = 0.0343)." (PMID 32650820, 2020).
osteoporosis (1 paper, 2024). A condition of reduced bone mass, with decreased cortical thickness and a decrease in the number and size of the trabeculae of cancellous bone (but normal chemical composition), resulting in increased fracture incidence. "As calcium and magnesium are key components of bone, we tested the hypothesis that Ghrelin-deficiency contributes to osteoporosis via reduced upregulation of the renal calcium channel TRPV5 and the heteromeric magnesium channel TRPM6/7." (PMID 38638279, 2024).
preeclampsia (1 paper, 2019). Preeclampsia is a hypertensive disorder of pregnancy that is characterized by new-onset hypertension with proteinuria presenting after 20 weeks of gestation, and depending on mild or severe forms may initially present with severe headache, visual disturbances, and hyperreflexia. "Interactions between RTKs, such as VEGFR and EGFR, TRPM6/7 and Mg2+, have also been implicated in preeclampsia." (PMID 30995736, 2019). "In a study examining placentas from women with preeclampsia compared to placentas from normotensive women, pre-eclamptic placentas had reduced expression of TRPM6 and TRPM7, which was linked to altered cellular Mg2+ homeostasis." (PMID 30995736, 2019). "Together these findings suggest an important relationship between VEGF, TRPM6/7 and Mg2+ in preeclampsia." (PMID 30995736, 2019).
prostate carcinoma (1 paper, 2023). A carcinoma that arises from epithelial cells of the prostate gland. "In this study, we measured the expression of the L-type and T-type voltage-gated calcium channels, the nonselective cation channels TRPM-6 and TRPM-7, and the selective calcium channel TRPV-6 in nontumorigenic prostate cells and hormone-dependent and hormone-resistant prostate cancer cells." (PMID 38131032, 2023).
Pruritus (1 paper, 2017). Pruritus is an itch or a sensation that makes a person want to scratch. "There have been reports that TRP channels other than TRPV3, such as TRPV1/4, TRPA1, and TRPM6/7 contribute to pruritus." (PMID 29140280, 2017).
rectum tumor (1 paper, 2019). "However, only the TCGA dataset contained rectum tumor samples, in which the expression profiles of KCNN2, STIM2 and TRPM6 followed that of the distal tumor samples." (PMID 31010205, 2019).
sarcopenia (1 paper, 2016). Progressive decline in muscle mass due to aging which results in decreased functional capacity of muscles. "Weight gain and lean body mass of Trpm6-deficient mice were reduced, as was the muscle fibre area of the gastrocnemius muscle of 12–13 week-old Trpm6-deficient mice indicative of sarcopenia." (PMID 27991852, 2016).
skin cutaneous melanoma (1 paper, 2022). "For the SNV percentage, the total deleterious mutation percentage (i.e., the number of samples with at least one deleterious mutation site/the number of samples with SNV mutation data) showed the highest deleterious mutation frequency of TRPM6 in skin cutaneous melanoma (SKCM)." (PMID 35493463, 2022).
testicular germ cell tumor (1 paper, 2025). A germ cell tumor arising from the testis. "In adrenocortical carcinoma (ACC) and testicular germ cell tumors (TGCT), TRPM6 exhibited a strong positive correlation with naive B cells (P < 0.01)." (PMID 41562086, 2025).
uterine serous carcinoma (1 paper, 2025). "TRPM6 demonstrated a significant positive correlation with TMB in uterine serous carcinoma (USC) and ACC (P < 0.05), whereas a robust negative association was observed in BLCA, COAD, and kidney renal papillary cell carcinoma (KIRP) (P < 0.05)." (PMID 41562086, 2025).
vitamin D deficiency (1 paper, 2019). A nutritional condition produced by a deficiency of VITAMIN D in the diet, insufficient production of vitamin D in the skin, inadequate absorption of vitamin D from the diet, or abnormal conversion of vitamin D to its bioactive metabolites. "Association of AmB/LE and vitamin D deficiency led to diminished glomerular filtration rate and increased tubular injury, evidenced by reduced renal protein expression of NaPi-IIa and TRPM6 leading to hyperphosphaturia / hypermagnesuria." (PMID 31295336, 2019).